TNF (tumor necrosis factor)
Diseases named in the same sentence as TNF in open-access papers (continued):
Sharing a sentence is not in itself a finding about the gene and the disease.
gastric cancer (continued). "Tumor necrosis factor α (TNF-α)-1031 T/C, -863 C/A and -857 C/T were also associated with higher risk of gastric cancer among smokers." (PMID 33557438, 2021). "TNFα is overexpressed in H. pylori infections, and it is related to high levels of infestation and an elevated risk of gastric cancer." (PMID 33498958, 2021). "H. felis infection is associated with reduced levels of interleukin-1β and tumor necrosis factor-α and increased level of interleukin-10, leading to the expression of key gastric mucosal cytokines and possibly gastric cancer." (PMID 32546214, 2020). "Polymorphism in the gene encoding proinflammatory cytokine TNF-α increased the risk of stomach cancer, and we also showed that TNF-α is required for the development of metaplastic hyperplasia in K19-C2mE mouse stomach." (PMID 30700829, 2019). "Macrophages are the primary producers of TNF, and increased levels of TNF have been associated with an increased risk of gastric cancer." (PMID 31636639, 2019). "In this process different cytokines take part e.g. IL-1, IL-17 (it is associated with a higher risk of developing gastric cancer connected with H. pylori colonization), tumor necrosis factor (TNF) α, toll-like receptors (TLRs)." (PMID 30123433, 2018). "The poor prognosis of gastric cancer and non-Hodgkin’s lymphoma has been linked to excessive amounts of the proinflammatory cytokines tumor necrosis factor and IL-1, respectively." (PMID 30469439, 2018). "CDX1 promoter methylation was highly consistent with NF-κB signal activation, but inversely associated with TNF-α expression in the carcinogen-induced stomach cancer development." (PMID 29467412, 2018). "A previous study showed that TXNIP inhibits HP-associated gastric cancer by inhibiting the induction of tumor necrosis factor-alpha, nuclear transcription factor-kappa B, and cyclooxygenase-2." (PMID 30008463, 2018). "Overall, the meta-analysis revealed an increased risk between the TNF-α T-857C polymorphism and gastric cancer susceptibility in T versus C model, heterozygote genetic model, and dominant genetic model." (PMID 28115787, 2016). "Expression of transcripts encoding multiple pro-inflammatory cytokines previously implicated in gastric cancer was also elevated, including IL-6, IL-11, IL-1β, and TNFα." (PMID 26859571, 2016). "A total of 9 relevant studies, consisting of 1897 patients and 3219 controls, were examined for the association between the TNF-α T-857C polymorphism and gastric cancer risk." (PMID 28115787, 2016). "This meta-analysis with published data suggested that the TNF-α T-857C polymorphism is a risk factor for gastric cancer, especially in Asian populations." (PMID 28115787, 2016). "With regard to the TNF-α T-857C polymorphism and gastric cancer susceptibility, the study of Cen and Wu was published in 2013." (PMID 28115787, 2016). "Currently, several molecular epidemiological studies have been conducted to investigate the association between the SNPs in TNF-α and gastric cancer risk." (PMID 26504356, 2015). "In Caucasian populations, they demonstrated a weak association between the TNF-α-308 A variant and gastric cancer risk." (PMID 26719751, 2015). "More so, functional genetic variants of the TNF-α gene have been associated with the susceptibility to gastric cancer." (PMID 25251497, 2014). "It has been suggested that over expression of TNF-α showed a significant severity-dose-response as risk markers from pre-neoplastic lesions to gastric cancer." (PMID 23326309, 2013). "Genotype and allele frequencies of TNF-α -308 G>A polymorphism among the cases and controls and their associations with risk of gastric cancer." (PMID 23326309, 2013). "Polymorphisms which increase IL1β and TNF expression have been associated with an increased risk of gastric cancer and its precursors." (PMID 24223737, 2013). "Polymorphisms in TNF leading to increased expression have been linked to increased risk of gastric cancers." (PMID 24223737, 2013).
gastric cancer (continued). "Accordingly, genetic polymorphisms associated with an elevated risk for gastric cancer have been identified in genes encoding interleukins (e.g. IL-1β), tumor necrosis factor (TNF), cyclooxygenase-2 (COX2), and other host factors." (PMID 24099599, 2013). "Second, H. pylori infection status is a well-known cause of gastric cancer and has been suggested to influence the expression of TNF- α." (PMID 23326309, 2013). "Polymorphisms in genes coding pro-inflammatory cytokines, such as interleukin 1 beta (IL-1β), interleukin-1 receptor antagonist (IL1Ra) and tumor necrosis factor-alpha (TNF-α) are accepted as risk factors of gastric cancer, depending on the geographic region." (PMID 22891666, 2012). "Especially, inflammatory cytokine gene polymorphisms (IL-1 gene cluster, TNF-α, IL-10, and IL-8) have been reported to be correlated with gastric cancer." (PMID 22189161, 2011). "For instance, cytokine polymorphisms of the IL-1β and TNF-α genes are associated with increased susceptibility to peptic ulcer disease and gastric cancer." (PMID 24212943, 2011). "Next, the CXCR4 expression within a co-culture system was examined, since tumor-associated macrophages also serve as a source of TNF-α in the gastric cancer microenvironment." (PMID 20699000, 2010). "The aim of this study was to assess the role of TNF gene variants and the combined effect between TNF genes and cigarette smoking in the development of gastric cancer in the Korean population." (PMID 19615068, 2009). "In single SNPs analysis, TNF-α-857 C/T containing the T allele was significantly associated with an increased risk of gastric cancer." (PMID 19615068, 2009). "The aim of this study was to investigate the role of TNF genetic variants and the combined effect between TNF gene and cigarette smoking in the development of gastric cancer in the Korean population." (PMID 19615068, 2009). "In the additive model which showed a linear trend effect, the CT genotype of TNF-α-857 showed a 1.6 fold increased risk for gastric cancer (95% CI 1.0–2.5) and the TT genotype of TNF-α-857 had a 2.6 fold increased risk (95% CI 1.0–6.4)." (PMID 19615068, 2009). "The combined effect between TNF gene and cigarette smoking can be a major risk factor for gastric cancer." (PMID 19615068, 2009). "Compared to the single SNP effect of the TNF-α-857 polymorphism, a greater odds ratio for haplotype-pairs including TNF-α-857 indicated that a synergistic interaction among TNF SNPs was more strongly associated with gastric cancer development." (PMID 19615068, 2009). "TNF-α-857 C/T containing the T allele was significantly associated with an increased risk of gastric cancer and a linear trend effect was observed in the additive model (OR = 1.6, 95% CI 1.0–2.5 for CT genotype; OR = 2.6, 95% CI 1.0–6.4 for TT genotype)." (PMID 19615068, 2009). "Haplotype-pairs effects of TNF genetic polymorphisms for gastric cancer stratified by smoking status in a nested case-control study within the KMCC 19,688 enrolled cohort members." (PMID 19615068, 2009). "The association between genetic polymorphisms of TNF and risk of gastric cancer in a nested case-control study within the KMCC 19,688 enrolled cohort members." (PMID 19615068, 2009). "MDR analysis for TNF SNPs and risk of gastric cancer associated with selected combination in MDR stratified by smoking status in a nested case-control study within the KMCC 19,688 enrolled cohort members." (PMID 19615068, 2009). "According to these papers, TNF-α-308 polymorphism had a significantly increased risk for gastric cancer but TNF-α-857 polymorphism only showed a marginally significant risk due to the small number of studies." (PMID 19615068, 2009). "CT genotype of TNF-α-857 showed a 1.7 fold increased risk for gastric cancer in the co-dominant and dominant models that were statistically significant (95% CI 1.0–2.8, identically in both models)." (PMID 19615068, 2009).
gastric cancer (continued). "Although studies have reported TNF can modify the risk of gastric cancer, the exact role of TNF as a gastric carcinogen is still controversial." (PMID 19615068, 2009). "In our study, TNF-α-857 C/T genetic variant containing the T allele was associated with a significantly increased risk for gastric cancer." (PMID 19615068, 2009). "Two recent meta-analyses assessed the association between TNF-α polymorphisms and risk of gastric cancer." (PMID 19615068, 2009). "Individual haplotype-pairs including TNF-α-1031, -863 and -857 were consistently associated with a significantly increased risk of gastric cancer." (PMID 19615068, 2009). "Given PPARα’s established role in restraining pro-inflammatory cytokines such as IL-6, IL-1β, and TNF-α, and the importance of inflammation in gastric cancer progression, we next assessed whether loss of PPARα elevates inflammatory mediators in GC cells." (PMID 40732023, 2025). "PD-L1 upregulation is a key mechanism of immune evasion in human gastric cancer and is associated with response to checkpoint inhibitor therapy; its regulation by TNF and STAT1 signaling in this model provides insights into the inflammatory control of immune checkpoint expression." (PMID 40673273, 2025). "The observed drop in TNF-α abundance suggests that these compounds may also alleviate inflammation, potentially diminishing the risk of inflammation-induced gastric cancer." (PMID 40573220, 2025). "Notably, polymorphisms like PSCA rs2294008 and TNF-α-308 G/A have shown strong correlations with gastric cancer susceptibility, particularly in Asian populations, suggesting a possible ethnic specificity in genetic risk factors." (PMID 39355481, 2024). "Meanwhile, gastric cancer tissue‐derived mesenchymal stem cells (GC‐MSCs) was proved to possess the ability to transfer into cancer‐associated fibroblasts (CAFs) under the stimulation of IL‐6 and TNF‐α which promote tumor progression." (PMID 38349050, 2024). "A case-control study suggests that potassium intake may regulate TNF-a production, with women having the lowest risk for gastric cancer found among those homozygous for TNF-a variants with the highest potassium intake." (PMID 39134992, 2024). "TNF was shown to have the strongest association with gastric cancer." (PMID 38612999, 2024). "SNP (−1,031 T/C) of the TNF-α may be a useful marker in the assessment of the risk of nutritional deficiencies in gastric cancer patients." (PMID 37533569, 2023). "Therefore, the aim of this study was to assess the TNF-α gene polymorphism (−1,031 T/C, rs1799964) as a predictor of malnutrition or prognostic factors in patients with gastric cancer." (PMID 37533569, 2023). "The absence of statistical significance could be probably explained by the recent findings that TNF-a variants related to colorectal and gastric cancer are population- and ethnicity-specific." (PMID 37762967, 2023). "IL-1β was reported to be associated with gastric cancer, and TNF-α could function as a tumor promoter in the development of cancer." (PMID 36249016, 2022). "TNF is an important inflammatory factor with various activities and allelic polymorphisms of TNF-A-308, TNF-B-1069, and TNF-B-252A/G, and other loci are associated with the incidence and susceptibility of gastric cancer." (PMID 36200190, 2022). "Furthermore, TNF-α expression in macrophages promotes tumorigenesis in the of Gan mouse stomach, a model of inflammation-associated stomach cancer caused by transgenic activation of PGE2 pathway and Wnt signaling." (PMID 30700829, 2019). "The results showed that the TNF-α expressions were significantly different between the metastatic group and non-metastatic group, and the logistic regression analysis indicated that TNF-α expression was a risk factor for peritoneal metastasis of gastric cancer." (PMID 30544870, 2018).
gastric cancer (continued). "A recent clinical study of patients with gastric cancer indicated that TNF-α expression was significantly different between patients with and those without peritoneal metastasis and was one of the risk factors for peritoneal metastasis of gastric cancer." (PMID 30544870, 2018). "Meta-analysis of association between TNF-α rs361525 polymorphism and gastric cancer." (PMID 29867530, 2018). "Single nucleotide polymorphisms have a principle role in gene expression of TNF-α and miRNAs which may lead to gastric cancer." (PMID 29118938, 2017). "TNF-α -1031 polymorphism has been reported to affect the risk of gastric cancer." (PMID 29118938, 2017). "H. pylori may increase risk of gastric cancer in part by activating NF-κB signaling, leading to secretion of pro-inflammatory cytokines such as tumor necrosis factor-α (TNF-α), interleukin-1 (IL-1β), interleukin-6 (IL-6) and interleukin-8 (IL-8)." (PMID 28030825, 2017). "In the stratified analysis by ethnicity for the TNF-α T-857C polymorphism and gastric cancer susceptibility, we found a significant risk in Asian populations rather than Caucasian populations, suggesting that the increased gastric risk may be ethnospecific." (PMID 28115787, 2016). "Hence, this is the most comprehensive meta-analysis that investigated the relationship between the TNF-α T-857C polymorphism and gastric cancer susceptibility." (PMID 28115787, 2016). "Besides IL-1and IL-1R1, many other cytokines and associated receptors, for example IL-6 and TNFα, are involved in the progression of gastric cancer and can activate NF-κB signaling." (PMID 26870992, 2016). "Also associated with increased risk of gastric cancer are: the allele TNF-308A in Caucasian populations and the IL8-251AA genotype in Asian populations." (PMID 24892619, 2013). "The association between TNF-α-308 G>A polymorphism and the progression of gastric cancer." (PMID 23326309, 2013). "Our study further identify the TNFA -308G>A polymorphism as a risk factor for gastric cancer in Chinese population, which may be of value in evaluating the role of TNF- α in gastric carcinogenesis." (PMID 23326309, 2013). "The combined effects between the TNF gene and smoking on gastric cancer risk were also evaluated." (PMID 19615068, 2009). "TNF-α-857 C/T polymorphism may play an independent role in gastric carcinogenesis and the risk for gastric cancer by TNF genetic effect is pronounced by cigarette smoking." (PMID 19615068, 2009). "Many studies have extensively investigated the association between TNF and gastric cancer." (PMID 19615068, 2009). "Therefore, several studies have examined the association of polymorphisms in tumour-necrosis factor-A gene (TNF-A) with gastric cancer risk." (PMID 18319718, 2008). "Nevertheless associations of the TNFα promoter -1031 polymorphism together with the -308 and -238 polymorphisms have also been made with respect to invasive breast carcinoma and an increased risk of gastric cancer." (PMID 18433468, 2008). "In this study, by testing serum TNF-α gene polymorphism (-1031T/C, rs1799964) in GC patients, it was found that the development of malnutrition in gastric cancer was associated with serum TNF-α gene polymorphism." (PMID 37533569, 2023). "Finally, TNF-α production induced by H. pylori infection may promote gastric cancer along with TNF-α polymorphisms may also increase risk of developing gastric cancer." (PMID 32216812, 2020). "In the present study of 1,125 participants (373 cases and 752 controls), we determined whether the dietary inflammatory index (DII) is associated with the risk of gastric cancer (GC) and investigated whether a TNF polymorphism (rs1799964) modifies this association." (PMID 32883994, 2020). "We therefore conducted an updated meta-analysis to obtain a more precise estimate of the association of TNF-α-238G/A polymorphism with gastric cancer (GC) risk." (PMID 30413607, 2018).
gastric cancer (continued). "Here, we showed that knock-down of OLFM4 effectively enhanced cell apoptosis in response to H2O2 or TNF α stimulation in MKN45 as well as SGC-7901 cells, suggesting blocking OLFM4 may increase the susceptibility of gastric cancer cells to the presence of H2O2 or TNF α." (PMID 22471589, 2012). "Thus, we hypothesized that genetic variants of TNF underlies the association with gastric cancer risk and/or their combined effect with cigarette smoking may modify the risk of gastric cancer." (PMID 19615068, 2009). "At the same time, studies have found that G protein coupled estrogen receptors prevent the activation of NF-κB promoter by Hp cytotoxin related gene A in gastric cancer cells, and inhibit the expression of tumor necrosis factor alpha (TNF-T), IL-6, and IL-1." (PMID 40463506, 2025). "These examples highlight the feasibility of pharmacologically targeting TNF-α, supporting further exploration of anti-TNF strategies in gastric cancer." (PMID 40299527, 2025). "TNF-α demonstrates a multifaceted role in gastric cancer immunotherapy, operating as both a tumor suppressor and a promoter depending on its position within the TME." (PMID 40309351, 2025). "While previous studies by the authors have examined various aspects of tumor marker interactions in gastric cancer, the specific relationship between TNF-α and the combined serological panel of AFP, CEA, CA19-9, and CA72-4 remains unexplored." (PMID 40299527, 2025). "These cutting-edge tactics match the dynamic nature of TNF-α therapy for gastric cancer, balancing the potent anti-cancer effects with the necessity of management and intentional administration." (PMID 40309351, 2025). "TNF-α is an integral component of the gastric cancer microenvironment, both reflecting and potentially driving disease severity." (PMID 40299527, 2025). "Clinical survival analysis identified four core proteins (CASP3, TNF, AKT1, and EGFR) whose abundance was associated with survival status in gastric cancer patients." (PMID 40573220, 2025). "The findings suggest that HDGF and TNFα act as independent signaling molecules in the progression of gastric cancer infected by H. pylori." (PMID 40661971, 2025). "In summary, we found that plasma TNF-α levels were significantly elevated in gastric cancer patients compared to controls (median 4.5 vs. 2.9 pg/mL, p = 0.014)." (PMID 40299527, 2025). "Tipα secreted from H. pylori stimulates gastric cancer development by inducing TNF-α, an endogenous tumor promoter." (PMID 40445003, 2025). "PTX3 expression is elevated in advanced gastric cancer samples via TNF-α/NF-κB activation, thus promoting cancer cell migration and the recruitment of macrophages." (PMID 41479916, 2025). "Within the gastric cancer cohort (n = 80), TNF-α levels demonstrated significant positive correlations with several tumor markers." (PMID 40299527, 2025). "These compounds showed anti-gastric cancer activity against the HGC-27 cell line by acting on TNF and T-cell receptor signaling pathways to diminish inflammatory factor production and promote apoptosis of gastric cancer cells." (PMID 40573220, 2025). "AGS gastric cancer cells have diminished levels of TNF-α, IL-1β, and interleukin-8 (IL-8) as a result of this activity, which also includes the production of the genes for cytotoxin-associated gene A (CagA) and vacuolating cytotoxin A (Vac A)." (PMID 40238859, 2025). "When studying stage IV gastric cancer, a 10-fold decrease in TNF-α was found compared to the control group (p1–5 < 0.001; p2–5 < 0.001; p3–5 < 0.001; p4–5 < 0.001)." (PMID 40806737, 2025). "When comparing the gastric cancer cohort (n = 80) with the control group (n = 20), clear distinctions emerged in the correlation patterns between TNF-α and key clinical variables." (PMID 40299527, 2025). "Our study provides new insights into the interplay between an inflammatory cytokine (TNF-α) and established tumor markers in gastric cancer." (PMID 40299527, 2025).